TLR3 (toll like receptor 3)
Diseases named in the same sentence as TLR3 in open-access papers (continued):
Sharing a sentence is not in itself a finding about the gene and the disease.
allergic rhinitis (5 papers, 2005 to 2025). Inflammation of the nasal mucous membranes caused by an IgE-mediated response to external allergens. "The mRNA expression of TLR3 was found to be elevated among patients with on-going symptomatic allergic rhinitis." (PMID 16146574, 2005). "This upregulation of TLR3 during pollen exposure is believed to contribute to airway inflammation, as evidenced by heightened production of antiviral proteins following dsRNA challenge in allergic rhinitis patients during pollen season." (PMID 39988665, 2025). "Upregulation of TLR3 has been reported in the nasal mucosa of patients with allergic rhinitis." (PMID 24886842, 2014). "An up-regulation of TLR2, TLR3 and TLR4 in the nasal mucosa of patients with symptomatic allergic rhinitis supports the idea of a role for TLRs in allergic inflammation." (PMID 16146574, 2005). "The present study was designed to quantify mRNA and protein expressions of TLR2, TLR3 and TLR4 in the nasal mucosa of patients with seasonal allergic rhinitis, before and after pollen exposure, and to compare these findings with data derived from healthy volunteers." (PMID 16146574, 2005).
atopic dermatitis (5 papers, 2014 to 2025). "We also reported that TLR3 regulated allergic reactions such as allergic conjunctivitis and contact and atopic dermatitis, because these allergic reactions were reduced in TLR3 knock-out mice." (PMID 36685889, 2022). "Clinically, increased TLR3 expression in the stratum corneum in atopic dermatitis patients is correlated with increased disease severity, which may be attributable to TLR3-induced production of type 2 cytokines that drive eosinophil recruitment." (PMID 39988665, 2025).
Chlamydia infection (5 papers, 2012 to 2024). "The TER in wild-type OE cells is significantly increased in response to Chlamydia infection after 6hrs post-infection when compared to infected TLR3-deficient OE cells and the mock controls." (PMID 30625140, 2019). "Fluorescent microscopy was also performed to assess protein expression levels and cellular distribution of various TJ proteins in WT and TLR3-deficient OE cells over the course of Chlamydia infection." (PMID 30625140, 2019). "IL-1β synthesized during early Chlamydia infection was also significantly diminished in TLR3-deficient mice between days 4 and 5, but was virtually identical to wild-type mice after day 5 of infection." (PMID 29624589, 2018). "One possible scenario that can provide some insight to this proposed TLR3-dependent mechanism of Chlamydia induced immunopathogenesis in mice intimates the possibility of a novel TLR3 PAMP (either bacterial or cellular) associated with Chlamydia infection." (PMID 29624589, 2018). "Based on these findings regarding IL-10’s purported role in suppressing IFN-β, we can extrapolate a similar role for IL-10 in the suppression of IFN-β during Chlamydia infection in TLR3-deficient mice." (PMID 29624589, 2018). "In this study, we further delineate the role of TLR3 in genital tract pathology associated with Chlamydia infection, by examining the impact that TLR3 signaling has on bolstering the host’s protective epithelial barrier that is designed to limit the spread of infection." (PMID 30625140, 2019). "The data from those previous experiments showed that TLR3 had a biological impact on the innate immune response to Chlamydia infection in mice, and we hypothesized that TLR3 deficiency might have a subsequent impact on Chlamydia’s ability to spread and ascend the female genital tract." (PMID 30625140, 2019). "However, further study is needed to address the interplay between TLR3 signaling and IL-10 synthesis in order to better understand how dysregulation of IL-10 synthesis during Chlamydia infection of TLR3-deficient mice leads to more substantial genital tract sequalae." (PMID 29624589, 2018). "Current immunological dogma proposes a role for TLR3 signaling in maintaining the integrity of epithelial barrier function during genital tract Chlamydia infection." (PMID 38172683, 2024). "Our data show that TLR3 plays a role in modulating epithelial barrier function during Chlamydia infection of epithelial cells lining the genital tract." (PMID 30625140, 2019). "We observed a differential distribution of JAM-1, ZO-1, and claudin-1 to the cellular TJs throughout Chlamydia infection that seemed to depend on the functionality of TLR3." (PMID 30625140, 2019). "In a seemingly contrasting finding, our results here suggest that TLR3 signaling modulates the release of this pro-inflammatory cytokine during the first week of Chlamydia infection in mice, suggesting instead that its synthesis is TLR3 dependent." (PMID 29624589, 2018). "The impact that this differential expression of inflammatory mediators has on the overall outcomes of Chlamydia infection in TLR3-/- mice is uncertain." (PMID 29624589, 2018). "In either scenario, the identification of the TLR3 PAMP that is presented during Chlamydia infection would represent a significant contribution to our understanding of TLR3 biology." (PMID 29624589, 2018). "Using the OE cells as a model to study in vitro Chlamydia infections, we showed that C. muridarum induces IFN-β in a mostly TLR3-dependent manner, and we were the first to demonstrate TLR3-specific immune response to Chlamydia infection in vitro." (PMID 25798928, 2015). "Interestingly, our data showed that some TJ genes were upregulated while some were downregulated in response to Chlamydia infection and that some were also differentially regulated dependent upon the functionality of TLR3." (PMID 30625140, 2019).
Chlamydia infection (continued). "Interestingly, the presence of CD4+ T-cells were markedly enhanced in the genital tract of TLR3-/- mice at this stage of Chlamydia infection." (PMID 29624589, 2018). "The data from these experiments also demonstrated that TLR3 had a biological impact on the innate immune response to Chlamydia infection in mice; however, the exact effect that TLR3 signaling had on the genital tract pathology of C. muridarum infection in mice was unclear." (PMID 29624589, 2018). "Our data proposes that the initial wave of IFN-β synthesized early during Chlamydia infection is TLR3-dependent and occurs through pathways involving IRF3; while late stage IFN-β synthesis is triggered by the type-1 IFN secreted into the supernatants, and signals through pathways that require IRF7." (PMID 25798928, 2015). "We hypothesized that either bacterial DNA or RNA were the likely PAMP(s) that binds to TLR3 during Chlamydia infection of OE cells." (PMID 25798928, 2015). "Furthermore, Derbigny and co-workers have recently reported TRIF dependent IFN-β production after Chlamydia infection of murine macrophages and attributed this to TLR3 mediated signaling." (PMID 22363584, 2012). "The ECIS data show that TLR3 deficiency in oviduct epithelium led to a more rapid decline in TER during Chlamydia infection, and the rate of TER decline was not affected by the addition of exogenous IFN-β which is known to restrict C. muridarum replication in these cells." (PMID 30625140, 2019). "Another possibility is that Chlamydia infection of reproductive tract epithelium somehow induces a cellular response resulting in the syntheses of cellular double-stranded RNAs, which could then bind-to and stimulate TLR3-dependent immune responses." (PMID 29624589, 2018). "This interplay between TLRs 2 and 3 is representative of a possible regulation of TLR2-dependent immune responses by TLR3, and that this mechanism of regulation may be important to help control outcomes of Chlamydia infection in mice; particularly early- and mid-infection." (PMID 29624589, 2018). "Because TLR3-/- mice exhibited increased genital tract shedding of Chlamydia throughout the first three weeks of infection, we next evaluated whether TLR3-/- mice also developed more severe pathology in the genital tracts during Chlamydia infection." (PMID 29624589, 2018). "However, the early IFN-β response to Chlamydia infection in OE cells is largely TLR3-dependent, which differs from the findings in peritoneal macrophages and implicates divergent pathways to IFN-β synthesis that converge and activate IRF3 in these two cell-types." (PMID 25798928, 2015). "Because TLR3 transcription levels are at its highest levels early during the course of Chlamydia infection, the TLR3 gene expression results suggest a more substantial role for TLR3 in the synthesis of IFN-β early during Chlamydia infection of OE cells as was previously reported." (PMID 25798928, 2015). "Though the relationship between TLR3 signaling and STING has not been investigated in OE cells, it is a strong possibility that these pathways intersect during Chlamydia infection in these cells." (PMID 25798928, 2015).
chlamydial infection (5 papers, 2016 to 2022). "Deficiency of TLR2 or TLR4 in macrophages significantly reduces TNF-α levels during chlamydial infection,while deficiency of TLR3 in epithelial cells increases its levels at the early stage of chlamydial infection." (PMID 34093528, 2021). "Surprisingly, our data show that CD4+ T-cells are significantly enhanced in the genital tract TLR3-/- mice during mid-stage Chlamydial infection." (PMID 29624589, 2018). "In this study, we further examine the role of TLR3 in the development of genital tract pathology during chlamydial infection." (PMID 29624589, 2018). "The activation of TLR3 following a chlamydial infection has also been recently demonstrated in human Sertoli cells, an epithelial cell line of the testis, suggesting that this immune mediator could also be involved in the recognition of C. trachomatis." (PMID 32050567, 2020). "Because TLR3-/- mice exhibited more obvious lymphocytic endometritis and salpingitis during middle stage of chlamydial infection, we further evaluated whether TLR3-/- mice also developed more severe hydrosalpinx in the upper genital tract." (PMID 29624589, 2018). "In addition, data from in vivo infection models demonstrated that TLR2 knockout mice had a more severe disease, as well as an intense and prolonged chlamydial infection, as compared to wild type mice, and TLR3 and STING played a key role in the activation of a multitude of inflammatory modulators." (PMID 32050567, 2020). "In contrast, the TLR3-/- mice secreted higher levels of IL-10, TNF-α and IFN-γ than wild-type mice at day 7 of infection, suggesting that TLR3 deficiency did not result in a global downregulation in synthesis of cytokines during early stages of chlamydial infection." (PMID 29624589, 2018). "By contrast, TLR3-mediated sensing of chlamydial infection in human Sertoli cells did not elicit the activation of the related pathways, namely NFkB and IRF3, as well as the subsequent cytokine production." (PMID 35174109, 2022). "Conversely, those patients with evidence of Chlamydial infection responding to antibiotics may populate a TLR3 agonist (rintatolimod) non-responder cohort." (PMID 27045557, 2016).
cholestasis (5 papers, 2018 to 2024). Impairment of the bile flow caused by obstruction within the liver, or outside the liver in the bile duct system. "TLR3 deficiency deteriorated the liver lesions induced by C. sinensis, with more pronounced bile duct degeneration, connective hyperplasia, and cholestasis than in WT mice." (PMID 37167198, 2023). "Infection of TLR3 KO mice with RRV resulted in bile duct obstruction of only 22.2%, a sharp contrast to the 100% of RRV-infected WT-BALB/c mice with obstructed bile ducts, though they experienced similar symptomatology and mortality." (PMID 38860860, 2024). "However, our data suggests that cholestasis and the consequent liver damage inhibits IFN induction following LCMV infection and TLR3 stimulation and accordingly drives excessive viral replication." (PMID 30111770, 2018). "More work is needed to define why TLR3 KO mice experience mortality without bile duct obstruction." (PMID 38860860, 2024). "There was a negative correlation between TLR3 and IFNL3 and the serum levels of GGT, suggesting that these two markers can efficiently suppress virus replication and influence the levels of one of the main characteristics of HCV infection: cholestasis (blockage of the bile ducts)." (PMID 34207750, 2021).
chronic hepatitis B (5 papers, 2016 to 2025). "This study investigates the TLR3 1377 C/T polymorphism’s association with clinical outcomes in chronic hepatitis B patients." (PMID 40299876, 2025). "The TLR3 1377 C/T polymorphism, particularly the CC genotype, may influence the clinical presentation of chronic hepatitis B, particularly in symptomatic cases." (PMID 40299876, 2025). "Univariate logistic regression analysis revealed a significant association of the TLR3 rs3775291 risk variant with a higher likelihood of development of active chronic hepatitis B (OR = 2.13 [95% CI: 1.54–2.95] p = 6.00 × 10−6) and with HBeAg positivity (OR = 2.10 [95% CI: 1.31–3.36] p = 0.002)." (PMID 30143709, 2018). "The TLR3 rs3775291 A allele was associated with a reduced likelihood of spontaneous HBsAg SC and HBeAg SC, and an increased risk of developing chronic hepatitis B. In haplotype analysis, the haplotype including both risk variants rs3775291A and rs5743305A had the lowest likelihood of HBsAg SC." (PMID 30143709, 2018). "It is worth saying that this study’s strength is its comprehensive analysis of various factors, including gender, HBeAg status, liver enzyme levels, and TLR3 SNP 1337 CT genotypes concerning chronic hepatitis B activity." (PMID 40299876, 2025). "In HBV infection, the AA for the TLR3 rs5743305 T/A variation was more frequent in the group with chronic hepatitis B compared to the control group." (PMID 40831704, 2025). "The clinical and epidemiological features of individuals with chronic hepatitis B are investigated in this case-control study, with particular attention paid to the distribution of genders, HBeAg status, liver enzyme levels, and TLR3 SNP 1337 CT genotypes in the Sudanese population." (PMID 40299876, 2025). "Other studies have also shown that, in liver tissue and peripheral blood mononuclear cells from patients with chronic hepatitis B (CHB), TLR3 expression itself is substantially reduced." (PMID 27121087, 2016).
clear cell renal carcinoma (5 papers, 2011 to 2025). A malignant epithelial neoplasm of the kidney characterized by the presence of lipid-containing clear cells within a vascular network. "TLR3 was found to be overexpressed in 139 of 189 (73.5%) cases of clear cell renal cell carcinoma and in 6 of 8 lung metastatic clear cell renal cell carcinoma compared to the very low expression in the normal kidney tissue." (PMID 35748782, 2022).
coronary artery disease (5 papers, 2022 to 2025). "Interestingly, the overexpression of TLR3 and TLR4 has been implicated in the severity of coronary artery disease." (PMID 37958848, 2023). "In the context of coronary artery disease (CAD), which is driven by both lipid accumulation and inflammation, the role of TLRs, particularly TLR3 and TLR4, has gained significant attention." (PMID 41311551, 2025). "Our data support a role for TLR3 in cardiac fibroblasts in contributing to the enhanced inflammatory state and reduced PCDHG expression previously observed in the diseased myocardium of patients with advanced coronary artery disease and aortic valve disease." (PMID 39828779, 2025). "The present study builds upon our previous findings in heart tissue from patients with advanced coronary artery disease and aortic valve disease, which demonstrated increased expression of TLR1, TLR3, and TLR7, along with elevated levels of their downstream signaling mediators." (PMID 39828779, 2025).
demyelinating disease (5 papers, 2011 to 2018). A broad group of disorders that affect the myelin sheaths that cover the neurons. "Our results showed that TLR3-deficient susceptible SJL mice accelerated the development of demyelinating disease, whereas TLR3-deficient resistant B6 mice remained disease free." (PMID 22189096, 2011). "To investigate the role of TLR3-mediated innate immune responses on the pathogenesis of TMEV-induced demyelinating disease, we utilized TLR3-deficient mice in both the resistant C57BL/6 (B6) and susceptible SJL/J backgrounds." (PMID 22189096, 2011). "Therefore, TLR3-mediated signals are important in protecting susceptible mice from the development of TMEV-induced demyelinating disease, although TLR3-mediated signals appear to play a minor role in resistant mice." (PMID 22189096, 2011). "In this study, we investigated the role of TLR3-mediated signaling in the development of TMEV-induced demyelinating disease." (PMID 22189096, 2011). "In this study, we examined the potential role of TLR3 in the progression of TMEV-induced demyelinating disease by utilizing TLR3 KO mice and administering TLR3 ligand." (PMID 22189096, 2011). "Therefore, the relative role of TLR3-mediated signaling in the development of TMEV-induced demyelinating disease remains to be determined." (PMID 22189096, 2011). "For example, in a study of TLR3-deficient mice infected with murine encephalomyelitis virus Taylor (TMEV), it has been suggested that TLR3 signaling may be either protective or pathogenic for the development of TMEV-induced demyelinating disease." (PMID 29264743, 2018). "However, the role of TMEV-induced TLR3 signaling in protection from and/or pathogenesis of demyelinating disease remains unknown." (PMID 22189096, 2011). "We have also reported that TLR3, MDA-5, IL-1β and type I IFNs play critical roles in the development of TMEV-induced demyelinating disease." (PMID 28445497, 2017). "However, it is not known whether TLR3-mediated signaling plays a protective or pathogenic role in the development of demyelinating disease." (PMID 22189096, 2011). "We investigated the role of TLR3-mediated signaling in the protection and pathogenesis of TMEV-induced demyelinating disease." (PMID 22189096, 2011). "An increased viral load in the absence of TLR3 signaling led to elevated cytokine production, cellular infiltration, and exacerbated development of demyelinating disease." (PMID 22189096, 2011).
Encephalopathy (5 papers, 2007 to 2022). Encephalopathy is a term that means brain disease, damage, or malfunction. "In addition, a missense mutation of TLR3 has been detected in a patient with influenza-associated encephalopathy." (PMID 23151015, 2012).
heart failure (5 papers, 2018 to 2025). Inability of the heart to pump blood at an adequate rate to meet tissue metabolic requirements. "Moreover, TLR3 was found as a marker predicting the risk of doxorubicin-induced heart failure." (PMID 34531911, 2021). "It is concluded that up‐regulated TLR3 expression and signalling contributes to persistent autophagy following MI, which promotes heart failure and lethality." (PMID 28945004, 2018). "In the mice subjected to MI‐induced persistent autophagy, TLR3‐KO attenuated autophagy, reduced infarct size and improved heart failure and survival." (PMID 28945004, 2018). "The knockout of TLR3 significantly attenuated autophagy, prevented heart failure and improved survival, which was abolished by an autophagy inducer." (PMID 28945004, 2018). "Despite that, this study demonstrates the induction of cardiac autophagy upon TLR3 activation, which contributes to the persistently activated autophagy, heart failure and lethality following MI." (PMID 28945004, 2018). "Germline knockout (KO) of TLR3 inhibited autophagy, reduced infarct size, attenuated heart failure and improved survival." (PMID 28945004, 2018). "Taken together, this study shows that TLR3 plays a role in persistent autophagy after MI, which contributes to heart failure and lethality." (PMID 28945004, 2018). "Besides, Minatoguchi's group reported that food restriction (FR) prevented post‐infarction heart failure by ‘enhancing autophagy’ 43, whereas we claim here that TLR3‐KO generated similar protection by ‘inhibiting autophagy’." (PMID 28945004, 2018).